PRL (prolactin)
Diseases named in the same sentence as PRL in open-access papers (continued):
Sharing a sentence is not in itself a finding about the gene and the disease.
hyperprolactinemia (continued). "Glucose intolerance was observed in response to HFD or chronic hyperprolactinemia separately, and importantly, intolerance was exacerbated in HFD animals that were also hyperprolactinemic, suggesting an aggravating effect of prolactin on altered glucose homeostasis induced by HFD." (PMID 35757410, 2022). "Patients who have not been pregnant or delivered often suffer from hyperprolactinemia or up-regulated prolactin receptors or hypersensitivity to the normally circulating prolactin." (PMID 35473758, 2022). "The 2011 Endocrine Society Hyperprolactinemia Guidelines suggest that dopamine agonist discontinuation should be considered after treatment for at least 2 years in patients with a normal serum prolactin and no visible tumor remnant on imaging." (PMID 36013562, 2022). "In the patient with recurrent hyperprolactinemia following previous TSS (Case 10), in whom recurrent tumor was localized within the left cavernous sinus, SRS was followed by a progressive fall in serum prolactin to near normal levels (1.4 × ULN)." (PMID 35608811, 2022). "Regardless of the nature of hyperprolactinemia, PRL excess is known to influence the orexigenic–anorexigenic systems that regulate appetite determining hyperphagia and increase in food intake, leading to weight gain till to overt obesity." (PMID 36237192, 2022). "Compared to both groups, baseline prolactin level and the rate of hyperprolactinemia did not significantly differ (17.73 ± 14.14 to 20.34 ± 23.01, p = 0.637, and 21% to 22%, p = 0.924)." (PMID 35612842, 2022). "notified that response to the combined therapy was not dependent on the presence of hyperprolactinemia or prolactin staining in tumor cells by immunohistochemistry." (PMID 35612842, 2022). "Due to the lack of data on pituitary damage and a slight increase in prolactin concentration, this symptom was interpreted as transient hyperprolactinemia in these patients." (PMID 35126755, 2021). "Since SSTR5 is more important in PRL release regulation, somatostatin analogues with improved selective binding affinity for SSTR5 subtype may be effective in the treatment of hyperprolactinemia." (PMID 34681905, 2021). "In the nonaripiprazole group, most patients with hyperprolactinemia underwent normalization of their prolactin levels." (PMID 33496984, 2021). "Br treatment significantly decreased serum PRL levels and reversed OXTR-induced hyperprolactinemia." (PMID 34099636, 2021). "DAs are also used to treat endocrine conditions, such as prolactin (PRL)-secreting adenoma, growth hormone (GH)- and GH/PRL-secreting adenoma, non-functioning pituitary adenoma, and idiopathic hyperprolactinemia." (PMID 33314003, 2021). "Six patients had mild hyperprolactinemia, and the levels of prolactin did not exceed 2 times the upper limit." (PMID 35140585, 2021). "In patients with risperidone-induced hyperprolactinemia, the administration of adjunctive aripiprazole has shown to be an effective treatment option for normalization of serum PRL levels with no changes in psychiatric or extrapyramidal symptoms." (PMID 34207687, 2021). "Acute hyperprolactinemia suppresses testosterone synthesis and male fertility by inhibiting the secretion of GnRH, while a moderate increase in circulating prolactin has been shown to suppress both LH and FSH but not testosterone." (PMID 33663539, 2021). "Without the use of PEG pretreatment, no commercial prolactin kits have been developed to accurately classify macroprolactin from true hyperprolactinemia." (PMID 34620143, 2021). "Since prolactin has been demonstrated as an inhibitor of SHBG, hyperprolactinemia observed in the present study may contribute to the reduced plasma levels of SHBG in HU group." (PMID 33663539, 2021). "Early remission, defined as a lack of hyperprolactinemia symptoms and normalization of serum prolactin concentration, was ascertained in all patients at 3 months." (PMID 32733387, 2020).
hyperprolactinemia (continued). "Serum PRL is ordinarily under 25 ng/L; a level above the normal upper limit is diagnosed as hyperprolactinemia as long as the sample is obtained without excessive stress challenges before venipuncture." (PMID 32982975, 2020). "Unlike the high PRL levels because of ovarian stimulation, pre-existing hyperprolactinemia before IVF/ICSI treatment puzzles physicians the most." (PMID 32982975, 2020). "Co-incidence between both macrorprolactinemia and monomeric hyperprolactinemia were noted; therefore, the presence of macroprolactinemia does not exclude the possibility of pituitary pathology particularly in case of post PEG PRL level above the normal reference range." (PMID 32550971, 2020). "In addition, hyperprolactinemia was seen, which indicates that GPR101 facilitates the enhanced secretion of both GH and PRL." (PMID 32958754, 2020). "As far as hyperprolactinemia is concerned, risperidone seems to induce it quite frequently, whereas aripiprazole does not seem to show any effects on prolactin (PRL) levels." (PMID 32265749, 2020). "The use of PRL lowering treatment in patients with hyperprolactinaemia secondary to chronic kidney or liver disease has not been investigated." (PMID 31847209, 2019). "A single PRL value above the upper limit of normal can be sufficient for confirmation of hyperprolactinaemia, provided blood sampling took place without excessive venepuncture stress." (PMID 31847209, 2019). "Patients in the non-clozapine group had higher prolactin level and higher percentage of hyperprolactinemia than the clozapine group and healthy controls (both p values < 0.001)." (PMID 30846868, 2019). "In addition to the local detection of PRL and PRLR, hyperprolactinemia was also reported in 36%11 and 44%36 of GBM patients." (PMID 31862900, 2019). "Prolactin secretion is regulated by dopamine, which was demonstrated using mice lacking the dopamine D2 receptor and exhibiting hyperprolactinemia." (PMID 31540087, 2019). "Nevertheless, according to the guidelines of the Endocrine Society, a single PRL level above the upper limit of normal confirms the diagnosis of hyperprolactinemia, as long as the serum sample was obtained without excessive venipuncture stress." (PMID 29768629, 2018). "In the second scenario, serum PRL evaluation is requested in the absence of complaints related to hyperprolactinemia." (PMID 29768629, 2018). "First, many of these studies did not differentiate between hyperprolactinemia-inducing antipsychotics and other drugs that do not raise serum PRL levels significantly." (PMID 29778097, 2018). "Of note, big prolactin and especially macroprolactin, due to their large size, have increased clearance time however do not contribute to hyperprolactinemia symptoms due to their biologic inactivity." (PMID 30627169, 2018). "While schizophrenia patients frequently show hyperprolactinemia as a consequence of antipsychotic treatment, several studies have reported an elevated prolactin level and its relation to cognitive function independent of medication." (PMID 30473669, 2018). "COMMENT 3: In cases of non-functioning pituitary adenomas, hyperprolactinemia results from stalk compression, and thus, prolactin (PRL) levels are modestly elevated (< 100 ng/mL) in the great majority of cases." (PMID 29768629, 2018). "To further test the association between hyperprolactinemia and activation of STAT5, we also stained for pSTAT5 in early lesions in mice treated with aripiprazole, which did not increase PRL." (PMID 29778097, 2018). "Non-functioning/silent lactotroph PitNET are PRL-immunoreactive tumors with no clinical signs of hyperprolactinemia, apart from elevated prolactin levels due to the stalk effect." (PMID 29275530, 2018). "After treatment with prolactin inhibitors, IGM also improved with hyperprolactinemia." (PMID 28321344, 2017).
hyperprolactinemia (continued). "Meanwhile, clinical studies failed to associate higher levels of PRL with PCOS and suggested that PCOS and hyperprolactinemia are two distinct entities although low prolactin can be a metabolic risk marker in PCOS patients." (PMID 27192117, 2017). "Three patients with residual tumors who received low-dose BRC treatment (cases number 2, number 14, and number 18) had normal PRL levels without clinical signs of hyperprolactinemia or mass effect." (PMID 27999593, 2016). "In women with elevated total prolactin levels, the mean total FSFI score inversely correlated with the total BDI-II score (women with macroprolactinemia: r = −0.26, p < 0.05; women with monomeric hyperprolactinemia: r = −0.41, p < 0.001)." (PMID 26902871, 2016). "Patient number 25 was initially sensitive to BRC treatment with the normalization of PRL level, so this patient was not included in the persistent hyperprolactinemia group." (PMID 27999593, 2016). "Furthermore, experimental lowering of prolactin concentrations decreases DHEAS, whereas DHEAS is elevated in hyperprolactinemia." (PMID 26840047, 2016). "Finally, in the context of pituitary adenoma, ETS2 is involved in inhibition of PRL gene expression, and therefore, the decrease of ETS2 mRNA in PRL tumors is consistent with the observed hyperprolactinemia." (PMID 26322309, 2015). "In patients with hyperprolactinaemia, metformin reduced plasma levels of prolactin, but did not affect circulating levels of thyrotropin and IGF-1." (PMID 25239203, 2015). "Recently, in a larger study (163 patients and 90 controls), Wang and colleagues found that hyperprolactinemia resulted in decreased total lumbar BMD in a group of male and female patients with schizophrenia (mean age of 36) who had been treated with PRL-raising APs for 12 months." (PMID 26309037, 2015). "Anterior pituitary lactotrophs secrete high levels of prolactin (PRL) in the absence of any hormone action in vitro, and such hyperprolactinemia (HPRL) is driven by spontaneous electrical activity and the accompanying voltage-gated calcium influx (VGCI)." (PMID 25754735, 2015). "In patients with hyperprolactinaemia, but not in the other groups of patients, metformin slightly reduced plasma levels of prolactin, and this effect correlated weakly with the metabolic effects of this drug." (PMID 25239203, 2015). "Prolactin might influence the metabolism of SHBG by its inhibiting hormonal influences and decrease of SHBG in hyperprolactinemia." (PMID 26635963, 2015). "DAs have strong suppressive effects on serum prolactin level regardless of etiology, so they tend to be used for both patients with prolactinoma and non-functioning pituitary adenoma with hyperprolactinemia." (PMID 25142896, 2014). "Compared to them, 9 (4.2%) patients in our series presented the serum prolactin concentration higher than 90 ng/ml in non-functioning pituitary adeonmas, and 53 (55.8%) of prolactinoma patients presented mild hyperprolactinemia less than 200 ng/ml." (PMID 25142896, 2014). "According to previously reported cut-off value of serum prolactin, mild hyperprolactinemia, which is considered non-definitive (border zone) concentration between prolactinoma and non-functioning pituitary adenoma, were defined as 90 – 200 ng/ml." (PMID 25142896, 2014). "Endocrine society clinical practice guidelines also recommend single measurement of serum prolactin without excessive stress for diagnosis of hyperprolactinaemia." (PMID 25518745, 2014). "Population: adult patients presenting with antipsychotic-induced hyperprolactinemia diagnosed by prolactin level with or without prolactin-related symptoms." (PMID 23936389, 2013). "On investigation, we found hyperprolactinemia and no other reasons for the high level of prolactin were detected." (PMID 23456048, 2013).
hyperprolactinemia (continued). "Macroprolactinemia is characterized by a large molecular mass of PRL (macroprolactin) as the main molecular form of PRL in sera, the frequent elevation of serum PRL (hyperprolactinemia), and the lack of symptoms." (PMID 23304187, 2012). "Dopamine agonists significantly reduced prolactin level (WMD, -45; 95% CI, -77 to -11) and the risk of persistent hyperprolactinemia (RR, 0.9; 95% CI, 0.81 to 0.99) but not other patient-important outcomes." (PMID 22828169, 2012). "Elevated serum PRL levels have been reported in patients with SLE, and hyperprolactinaemia occurs in approximately 15–31% of patients with SLE, and these elevated PRL levels do appear to correlate with clinical disease activity, as well as antinuclear antibody and anti-dsDNA titreS." (PMID 22924044, 2012). "Studies have reported varied elevations in basal circulating prolactin measures with SSRI use – often minimal to moderate increases in prolactin levels that are not necessarily classified as hyperprolactinemia." (PMID 23227451, 2012). "Macroprolactinemia is characterized by a lack of clinical symptoms of hyperprolactinemia and several studies using different PRL bioassay systems showed that the bioactivity of macroprolactin is low." (PMID 23304187, 2012). "Of these, 18 had a report of hyperprolactinemia based on abnormal laboratory values but had no clinical symptom related to prolactin." (PMID 22676070, 2012). "Given that a hormone provocation test showed a marked increase in the PRL level from 7.1 ng/mL before provocation to 142.7 ng/mL 30 minutes after provocation with TRH, our patient was considered to have latent hyperprolactinemia with abnormal lactation and menstruation." (PMID 22152284, 2011). "Six children (one girl, five boys) had prolactin levels above the upper normal limit, but no participant showed clinical signs of hyperprolactinemia." (PMID 21489232, 2011). "The pattern of hyperprolactinemia after r-hPRL administration does not perfectly replicate physiological or pathological hyperprolactinemia, however, it should be similar to the prolactin increase induced by metoclopramide." (PMID 17650319, 2007). "When switching towards a prolactin-sparing antipsychotic is not feasible, adjunctive use of aripiprazole - a dopamine D2 partial agonist - has emerged as a validated strategy to mitigate hyperprolactinaemia without compromising antipsychotic efficacy." (PMID 42144793, 2026). "This case report explores the diagnostic challenges and therapeutic approach in a patient presenting with idiopathic hyperprolactinemia while discussing the potential implications of prolactin dysregulation on mood disorders as a possible, but not definitive, clinical manifestation." (PMID 41510476, 2025). "In addition, an overproduction of prolactin and its reduced clearance in patients with CKD lead to hyperprolactinemia, resulting in an inhibition both of the pulsatile GnRH secretion and of the mechanism of positive feedback response of estrogens to gonadotropin secretion." (PMID 40283649, 2025). "In general, obesity in patients with hyperprolactinemia is not an uncommon phenomenon, as high PRL levels can contribute to obesity, although the exact mechanism remains unclear." (PMID 40113928, 2025). "Since hyperprolactinemia is present in nearly 30% of PCOS cases, this study aims to assess the impact of cabergoline on androgen levels and clinical outcomes in PCOS with elevated prolactin cases, discussing these findings with the results in prolactinoma cases." (PMID 40399716, 2025). "Prolactin levels should be checked to rule out hyperprolactinemia, which may result from hypothalamic or pituitary disorders and can contribute to hirsutism by increasing adrenal DHEA-S production." (PMID 40861719, 2025). "In addition, hyperprolactinemia influences appetite regulation and increases food intake, leading to weight increase, regardless of PRL metabolic effect." (PMID 38370355, 2024).
hyperprolactinemia (continued). "However, in the Brazilian Multicenter Study on Hyperprolactinemia, there was considerable overlap in prolactin levels among the different etiologies of nonphysiological hyperprolactinemia." (PMID 39420933, 2024). "The current standard in psychiatric practice is not to measure serum prolactin unless the patient becomes symptomatic, but hyperprolactinemia may be asymptomatic in the short term, and in the long term, there is potential for serious sequelae." (PMID 38352655, 2024). "However, there was considerable overlap in prolactin values regardless of the etiology of the hyperprolactinemia." (PMID 39420933, 2024). "The occurrence of mild hyperprolactinemia that is not consistent with the clinical presentation may be due to pulsatile prolactin secretion." (PMID 38578472, 2024). "Therefore, it is possible that the incidence of hyperprolactinemia is underestimated, as prolactin levels are not generally measured in the follow-up of these patients in the absence of suspicious clinical manifestations." (PMID 39062243, 2024). "Interestingly, none of the cited clinical studies on the impact of prolactin/hyperprolactinaemia on endometriosis and endometriosis-related infertility have reported the mentioned factors as exclusion criteria." (PMID 39407928, 2024). "Hence, the higher prolactin levels in FEP patients at baseline were not considered to be hyperprolactinemia." (PMID 37603404, 2023). "Finally, prolactin levels normalized in 71.4% of cases (30/42), while no cases of new hyperprolactinemia were detected after surgery." (PMID 37222882, 2023). "Our analysis supported that the increase in the treatment dose did not increase the incidence of hyperprolactinemia, which is also consistent with the conclusion of previous studies that “different doses of BNS did not cause a significant increase in blood prolactin levels”." (PMID 37803378, 2023). "In view of the exclusion of mixed prolactinoma, the pituitary stalk effect might contribute to the slight elevation of PRL in two of our patients without any symptoms or signs of hyperprolactinemia." (PMID 37324275, 2023). "The impact of metformin on plasma prolactin may be also different in women with tumor-induced and/or severe hyperprolactinemia, not participating in the current study." (PMID 37297964, 2023). "Different effects on prolactin levels allow us to conclude that, from a hormonal point of view, combined oral contraceptive pills are inferior to cabergoline but do not seem to exacerbate existing hyperprolactinemia." (PMID 37176648, 2023). "Of note, hyperprolactinemia does not disturb glucose homeostasis in global D2R knockout mice, indicating that central dopaminergic system is crucial for the metabolic effects of PRL." (PMID 36993818, 2023). "One patient had hyperprolactinaemia (4xULN) with amenorrhoea but without PRL immunopositivity." (PMID 37851558, 2023). "Moreover, the proportion of patients with hyperprolactinaemia and mean serum PRL levels were not significantly different between patients with unilateral breast diseases and those with bilateral breast diseases." (PMID 36845388, 2023). "This mild prolactin elevation in non-prolactin-producing lesions could be explained by the pituitary stalk effect, the most recognized hypothesis for hyperprolactinemia in nonfunctioning pituitary adenomas." (PMID 36147567, 2022). "Regarding hyperprolactinemia in non-pregnant status, a study in 1977 showed a decrease in glucose tolerance and hyperinsulinemia, so the authors suggested a diabetogenic effect of PRL in hyperprolactinemic patients." (PMID 36704037, 2022). "In addition, while hyperprolactinemia is common in patients with adenomyosis, the exact role of PRL in inducing the condition has not been fully characterized." (PMID 35330066, 2022).